CELSR2 (cadherin EGF LAG seven-pass G-type receptor 2)
Description:
Receptor that may have an important role in cell/cell signaling during nervous system formation.
Synonyms: CDHF10; EGFL2; KIAA0279; MEGF3; Flamingo1; ADGRC2
Tractability: Antibody: UniProt places it where antibodies can reach, with medium confidence; UniProt predicts a signal peptide or a membrane-spanning region; its Gene Ontology location is reachable by antibodies, with medium confidence. PROTAC: ubiquitination databases record sites on it; its protein half-life has been measured.
Gene: Protein-coding gene on chromosome 1 (109,249,539 to 109,275,751, forward strand). Ensembl gene ENSG00000143126.
Subcellular location: Cell membrane
Subcellular location (Human Protein Atlas): Cytosol; Vesicles
Gene Ontology:
Molecular function: G protein-coupled receptor activity; calcium ion binding; transmembrane signaling receptor activity
Biological process: axonogenesis; cell-cell adhesion mediated by cadherin; dendrite morphogenesis; G protein-coupled receptor signaling pathway; homophilic cell-cell adhesion; neural plate anterior/posterior regionalization; regulation of cell-cell adhesion; regulation of DNA-templated transcription; Wnt signaling pathway; Wnt signaling pathway, planar cell polarity pathway; animal organ development; anterior/posterior pattern specification; cell adhesion; cell surface receptor signaling pathway; nervous system development; plasma membrane bounded cell projection organization; signal transduction
Cellular component: adherens junction; cytoplasm; membrane; plasma membrane
Genetic constraint (gnomAD): Loss-of-function variants: 81 observed, 246.11 expected, observed/expected ratio (o/e) 0.33, 90% interval 0.27 to 0.4. The upper end of that interval is the gene's LOEUF score, 0.4, which puts it in group 1 of 6, group 1 being the genes least tolerant of losing a copy. Missense variants: 3,344 observed, 4,023.2 expected, observed/expected ratio (o/e) 0.83, 90% interval 0.81 to 0.86. Synonymous variants: 1,713 observed, 1,702.6 expected, observed/expected ratio (o/e) 1.01, 90% interval 0.97 to 1.05.
Homologues: Orthologues: chimpanzee CELSR2 (99% identical), macaque CELSR2 (99% identical), dog CELSR2 (97% identical), guinea pig CELSR2 (96% identical), pig CELSR2 (96% identical), rat Celsr2 (96% identical), mouse Celsr2 (96% identical), rabbit CELSR2 (95% identical), zebrafish celsr2 (63% identical), tropical clawed frog celsr2 (60% identical), Drosophila melanogaster stan (38% identical), Caenorhabditis elegans fmi-1 (26% identical), and 2 more. Paralogues in human: CELSR1 (57% identical), CELSR3 (52% identical), FAT1 (21% identical), FAT3 (21% identical), FAT2 (18% identical), FAT4 (18% identical).
Diseases named in the same sentence as CELSR2 in open-access papers:
CELSR2 is named in the same sentence as 52 diseases in open-access papers, as found by Europe PMC text mining. Sharing a sentence is not in itself a finding about the gene and the disease. The quoted sentences say what the papers report.
coronary artery disease (11 papers, 2014 to 2025). "CELSR2 in the cholesterol gene cluster shows a significant association with coronary artery disease and its single nucleotide polymorphism regulates plasma cholesterol levels." (PMID 28079101, 2017). "The IGFBP‐3‐increasing allele of SNP rs646776 (CELSR2 locus) was associated with increased risk of coronary artery disease (P = 9.4 × 10−15)." (PMID 27329260, 2016). "Although the underlying mechanism remains unclear, previous GWASs have identified an association between CELSR2 and coronary artery disease as well as serum cholesterol metabolism." (PMID 40649979, 2025). "Also, CELSR2 variants have been found to be associated with stroke and coronary artery disease through GWAS and meta-analyses; however, replication studies failed to confirm these findings." (PMID 37422595, 2023). "Additionally, we showed that CELSR2 is also linked with coronary artery disease in South Asians." (PMID 40689090, 2025). "CELSR2 is part of the CELSR2-PSRC1-SORT1 gene cluster, and was previously associated with coronary artery disease and circulating lipid levels." (PMID 28480134, 2017). "CELSR2 and PSRC1 (rs599839) have been associated with both coronary artery disease and total cholesterol concentration." (PMID 24725463, 2014).
Hydrocephalus (8 papers, 2013 to 2024). Hydrocephalus is an active distension of the ventricular system of the brain resulting from inadequate passage of CSF from its point of production within the cerebral ventricles to its point of absorption into the systemic circulation. "Mutations in mouse Celsr1, for example, cause severe defects in neural tube closure, and Celsr2 mutations cause defects in motile cilia formation leading to fatal hydrocephalus." (PMID 36712970, 2022). "Celsr2 is a planar cell polarity gene, and mutation results in hydrocephalus through ependymal cilia dysfunction." (PMID 35047005, 2021). "In CELSR2-deficient mice, the development and planar organization of ependymal cilia are compromised, leading to fatal hydrocephalus." (PMID 29240829, 2017). "Mice missing the PCP genes Celsr2 and Celsr3 develop hydrocephalus linked to defective motile cilia." (PMID 27055101, 2016). "It was shown that the ciliary defect in ependymal cells of the Celsr2/3- deficient mice developed hydrocephalus, owing to the impaired CSF circulation." (PMID 24236178, 2013). "Mice deficient in Celsr2 impaired ciliogenesis in ependymal cells, resulting in hydrocephalus." (PMID 26989192, 2016). "The disruption of ependymal planar polarity and CSF circulation, as evidenced by the downregulated polycystin 1 (PKD1) and CELSR2, is also consistent with established hypotheses of hydrocephalus development." (PMID 39118132, 2024). "The mutant genes related to motile cilium dysfunction on ependymal cells, and consequent hydrocephalus development may include Ccdc39, Celsr2, Celsr3, Cetn2, Dvl, Foxj1, Hydin, Mdnah5, Pkd1, Tg737, Daple, Dnah14, Cfap43, Cwh43, Eml1, Fmn2, Tmem67, and Zcchc8." (PMID 35047005, 2021). "Importantly, ablation of Celsr2 results in a hydrocephalus phenotype almost identical to the one we describe here." (PMID 27055101, 2016). "However, many developed hydrocephalus postnatally (not shown), also in line with prior reports of a different Celsr2 allele." (PMID 36712970, 2022).
breast carcinoma (7 papers, 2012 to 2022). "In breast cancer cells, based on immunohistochemical investigation, the role of CELSR2 in the pathogenesis of human mammary neoplasia was suggested due to the increased cytoplasmic staining compared to benign epithelium cells." (PMID 35761157, 2022). "In breast cancer cells, CELSR2, together with inhibitor of growth 4 (ING4) displayed increased cytoplasmic staining compared to benign epithelium cells, suggesting a possible role of both genes in the pathogenesis of human mammary neoplasia." (PMID 32293343, 2020). "The expression of CELSR2 protein was increased in the cytoplasm of breast cancer cells, but its possible function in cancer is unclear." (PMID 30809968, 2019). "Also, differential gene expression patterns of CELSR2 were identified in different breast cancer subtypes, as CELSR2 was downregulated in HER2-positive breast carcinoma compared with HER2-negative cancers." (PMID 35761157, 2022). "Studies have reported that CELSR2, ETV6, MGAT1, and RFX5 were associated with breast cancer." (PMID 35071020, 2021). "In breast cancer, CELSR2 was down-regulated in HER2-positive breast carcinoma." (PMID 32293343, 2020). "“Celsr2 was down-regulated in one cell line and in 7% of breast cancers”." (PMID 23216862, 2012). "Therefore, the role or CELSR2 can be hypothesized to be related to an altered GC response in breast cancer, but this biological link needs to be further investigated and confirmed." (PMID 35761157, 2022).
Joubert syndrome (5 papers, 2017 to 2025). Joubert syndrome (JS) is characterized by congenital malformation of the brainstem and agenesis or hypoplasia of the cerebellar vermis leading to an abnormal respiratory pattern, nystagmus, hypotonia, ataxia, and delay in achieving motor milestones. "Heterotopias were also detected in a Joubert syndrome patient carrying a mutation in the CELSR2 gene coding for a planar cell polarity protein essential for neural progenitor cell fate decision, neural migration, axon guidance, and neural maturation." (PMID 40956303, 2025). "Compound heterozygosity for mutations in CELSR2 have recently been suggested to cause Joubert syndrome, a ciliopathy disorder, in a young girl." (PMID 29240829, 2017). "Mutations in the cadherin epidermal growth factor laminin G seven-pass G-type receptor 2 gene (CELSR2) are thought to be responsible for Joubert syndrome, a disease with a high degree of autistic features." (PMID 34523068, 2022).
hepatocellular carcinoma (4 papers, 2020 to 2025). A malignant tumor that arises from hepatocytes. "Studies have shown that the expression of CELSR2 is significantly increased in hepatocellular carcinoma and can be used as a new prognostic biomarker for hepatocellular carcinoma." (PMID 41184253, 2025). "The results showed that CELSR2 was upregulated in hepatoma cell lines, especially in HepG2 and Hepa3B compared with LO2 (p < 0.01)." (PMID 32293343, 2020). "To confirm the conclusions above, we measured the expression level of CELSR2 in cultured hepatoma cell lines and HCC specimens." (PMID 32293343, 2020). "Likewise, it was reported that CELSR2 expression increase was accompanied with short OS in patients with hepatocellular carcinoma." (PMID 41184253, 2025). "(2020) confirmed that flamingo subfamily Cadherin EGF LAG seven-pass G-type receptor 2 (CELSR2) is significantly overexpressed in hepatocellular carcinoma and may serve as a novel prognostic biomarker." (PMID 33304656, 2020). "CELSR2 is postulated to be a receptor involved in contact-mediated communication; however, the specific function of this particular member has not been determined in hepatocellular carcinoma (HCC)." (PMID 32293343, 2020).
dyslipidemia (3 papers, 2011 to 2023). "No previous research was found associating the presence of the risk variants found in CELSR2 and CREB3L3 with alterations in the lipid profile or risk of suffering from dyslipidemia." (PMID 37065472, 2023). "Rs12740374 in CELSR2/PSRC1/SORT1 cluster was associated with two lipid traits: total cholesterol and dyslipidemia in our study, which is closely related with previously reported associations with LDL cholesterol and lipoprotein-associated phospholipase A2 activity and mass." (PMID 30704471, 2019).
Hypercholesterolemia (3 papers, 2022 to 2025). An increased concentration of cholesterol in the blood. "CELSR2, which encodes a transmembrane protein involved in cell adhesion and lipid metabolism regulation, has SNPs rs646776 for Pure hypercholesterolaemia and rs660240 for IHD." (PMID 38144368, 2023). "We also conducted an additional gene co-localisation analysis, identifying four genes, namely CELSR2, PCSK9, LPA, and APOE, co-localised with hypercholesterolaemia and IHD." (PMID 38144368, 2023). "Our analysis identified four colocalized genes, CELSR2, PCSK9, LPA, and APOE, that are involved in lipid metabolism and may contribute to the development of both Pure hypercholesterolaemia and IHD." (PMID 38144368, 2023).
liver cancer (3 papers, 2020 to 2023). An epithelial or non-epithelial malignant neoplasm that arises from the liver. "CELSR2 deficiency impaired cell proliferation of hepatocytes, liver cancer cells, and Schwann cells." (PMID 37270544, 2023). "Our in vitro results indicated that the depletion of CELSR2 inhibited liver cancer cell proliferation and invasion." (PMID 32293343, 2020). "However, at both the mRNA and protein levels, the expression of CELSR2 was significantly upregulated in liver cancer tissues and liver cancer cell line (e.g., Hep G2) compared with other organ tissues and cancer cell lines." (PMID 32293343, 2020). "Considering genetic alterations or dysregulated amplification is believed to play an important role in the development of many tumors, we thus explored the intrinsic carcinogenesis mechanism of CELSR2 in liver cancer by detecting the genetic alterations of CELSR2." (PMID 32293343, 2020).
myocardial infarction (3 papers, 2011 to 2019). Gross necrosis of the myocardium, as a result of interruption of the blood supply to the area, as in coronary thrombosis. "For example, one of the strongest associations for myocardial infarction lies in-between the CELSR2 and PSRC1 genes on chromosome 1p13, but a careful screen of genes whose expression was affected by the risk allele implicated the more distal SORT1 gene." (PMID 29988018, 2018). "Furthermore, a single nucleotide polymorphism (SNP) near CELSR2 on chromosome 1p13 (homologous to CELSR1) is associated with LDL cholesterol and myocardial infarction in a meta-analysis study by Myocardial Infraction Genetics Consortium." (PMID 21698157, 2011).
Stroke (3 papers, 2020 to 2024). Sudden impairment of blood flow to a part of the brain due to occlusion or rupture of an artery to the brain. "CELSR2, ABO, LPA, APOE, FGF5 and ZPR1 were related to both CHD and HF, while SH2B3 and FURIN were shared between CHD and stroke on MR analysis." (PMID 39322770, 2024).
diabetes (2 papers, 2020 to 2025). "The greatest increases in methylation in Wnt11, Celsr2 and Adcy3 could indicate future routes of investigation to elucidate the potential of PEA in NASH treatment, especially given their associations with obesity and diabetes." (PMID 40153413, 2025).
diabetes mellitus type 2 (2 papers, 2017 to 2020). "We found evidence for novel RV associations at CELSR2, SARS and FAM63B, of which common variation at CELSR2 has been previously associated with blood lipids, and at SARS/CELSR2 with type 2 diabetes, while FAM63B has no reported links with blood lipid levels." (PMID 28537275, 2017).
endometrial cancer (2 papers, 2019 to 2023). Primary or metastatic malignant neoplasm involving the endometrium (mucous membrane that lines the endometrial cavity). "Another E2-responsive gene CELSR2 is negatively associated with the overall survival time of endometrial cancer patients." (PMID 37270544, 2023).
Obesity (2 papers, 2015 to 2025). Accumulation of substantial excess body fat. "PEA treatment restored the methylation status of key genes involved in epigenetic modifications and induced differential methylation of genes associated with obesity and T2DM such as Adyc3, Celsr2, Fam63b." (PMID 40153413, 2025).
scoliosis (2 papers, 2017 to 2019). A congenital or acquired spinal deformity characterized by lateral curvature of the spine. "Recently, a rare variant of cadherin EGF LAG seven pass G-type receptor 2 (CELSR2) was co-segregating with scoliosis in Swedish-Danish patients." (PMID 30598481, 2019). "The penetrance of scoliosis in carriers of the CELSR2 variant in the present study is incomplete, suggesting additional unknown modifiers of disease risk (genetic or environmental)." (PMID 29240829, 2017).
atherosclerosis (1 paper, 2025). A disease characterized by the build-up of fatty material and calcium deposition in the arterial wall resulting in partial or complete occlusion of the arterial lumen. "CELSR2, FN1, SPARCL1, APOE, LPA, APOA5, and TGFB1 exhibit causal associations with both atherosclerosis and four cardiovascular diseases, suggesting their potential as therapeutic targets for atherosclerosis." (PMID 40649979, 2025). "Additionally, CELSR2 negatively regulates JNK signaling, which affects the Wnt/β-catenin pathway, and the Wnt pathway is directly linked to VSMC proliferation in neointima formation during atherosclerosis." (PMID 40649979, 2025). "The three most promising proteins (CELSR2, FN1, and SPARCL1) were identified as potential therapeutic targets for atherosclerosis, while APOE, LPA, APOA5, TGFB1, and AGER also hold potential as drug targets for the disease." (PMID 40649979, 2025).
cardiac hypertrophy (1 paper, 2022). "In our study, we found that the mmu-Ryr2_0040---miR-103-3p---Celsr2/Prmt8 axis may be a novel target in cardiac hypertrophy." (PMID 36003513, 2022).
cerebrovascular disease (1 paper, 2022).
ciliopathy (1 paper, 2016). A genetic disorder of the cellular cilia or the cilia anchoring structures, the basal bodies, or of ciliary function. "Of the remaining 40 families, nine (22.5%) had variants in eight novel candidate ciliopathy genes (TXNDC15, TRAPPC3, EXOC3L2, FAM98C, C17orf61, LRRCC1, NEK4, and CELSR2)." (PMID 27894351, 2016).
coloboma (1 paper, 2018). An abnormality in which a part of a structure in one or both eyes is missing. "In examining the prioritized list of rare variants identified in superior coloboma patients, we note rare variants in NKD1, CELSR2, FZD4, SCRIB, and WNT9B (components of canonical or non-canonical Wnt pathways)." (PMID 29522511, 2018).
craniorachischisis (1 paper, 2016). Craniorachischisis is the most severe form of neural tube defect in which both the brain and spinal cord remain open to varying degrees. "However, the phenotypes associated with the disruption of Vangl2 (ablation, looptail mutations) are characterized by serious neural issues such as craniorachischisis and other severe neural tube defects, a phenotype not observed in NHERF1-/- or Celsr2/3-/- animals." (PMID 27055101, 2016).
depression (1 paper, 2019). "Moreover, GPCRs (including ADGRA1, ADGRV1, CELSR2, and S1PR5) previously reported to be implicated in the physiopathology and pharmacology of depression were also significantly altered." (PMID 30983951, 2019).
dyslipidaemia (1 paper, 2025). "Our study highlighted potential causal links between plasma proteins, dyslipidaemia, and CVDs in South Asians and highlighted protein targets, including CELSR2, PCSK9, ANGPTL3, and Apolipoprotein(a) (LPA)." (PMID 40689090, 2025). "Given CELSR2 is a transmembrane receptor, and our study advised that CELSR2 abundance is inversely associated with plasma LDL-C level and can protect against CAD, activating CELSR2 could hold promise for treating dyslipidaemia and CAD." (PMID 40689090, 2025). "Our study confirmed key proteins (PCSK9, ANGPTL3, LPA), identified potential novel targets (GSTA1, GSTA3, EPPK1, PECR, and PLA2G15), and strengthened evidence for CELSR2 and GAS6 in dyslipidaemia." (PMID 40689090, 2025).
Encephalocele (1 paper, 2018). A neural tube defect characterized by sac-like protrusions of the brain and the membranes that cover it through openings in the skull. "Case NTD_122 with CELSR2 p.Arg1990His and CELSR3 p.Argy1194His had encephalocele." (PMID 29618362, 2018).
endometrial adenocarcinomas (1 paper, 2020). "In the endometrial adenocarcinomas, induction of CELSR2 could be found in the process of carcinogenesis." (PMID 32293343, 2020).